BRCA1 (BRCA1 DNA repair associated)
Diseases named in the same sentence as BRCA1 in open-access papers (continued):
Sharing a sentence is not in itself a finding about the gene and the disease.
breast cancer (continued). "Hereditary breast and ovarian cancer (HBOC) syndrome is characterized by autosomal dominant inheritance patterns caused by pathogenic variants in the germ line of Breast Cancer 1/2 (BRCA1/2)." (PMID 38524651, 2024). "Mutations in the breast cancer 1 gene (BRCA1) and breast cancer 2 gene (BRCA2) are among the most well‐known causes of autosomal dominant breast cancer." (PMID 38140764, 2024). "Mutations in the BRCA1 gene impair DNA repair, increasing susceptibility to various cancers, especially breast cancer." (PMID 38398090, 2024). "The trial results showed that the addition of olaparib reduced the risk of invasive disease recurrence or death by 42% in patients with high-risk, early-stage breast cancer and BRCA1/2 mutations." (PMID 38791944, 2024). "Experiments have showed that loss of HR proteins such as BRCA1/2 in breast cancer cells stimulate the synthetic lethality of PARG-inhibiting cells, and the PARG inhibitor induces cell death of BRCA mutated or olaparib-resistant breast cancer cells." (PMID 39334297, 2024). "It is estimated that female carriers of BRCA1/2 PVs are at a 69–72% risk of developing breast cancer by 80 years of age." (PMID 39682099, 2024). "Elevated dietary iron intake has been identified as a contributor to oxidative stress and DNA damage, thereby increasing the risk and recurrence of breast cancer, particularly in BRCA1 carriers and ER−/PR− subtypes during chemotherapy." (PMID 38140764, 2024). "We ectopically overexpressed Gata3 in Brca1-deficient mammary tumor cells and then treat them with OLA." (PMID 38627785, 2024). "In Korea, BRCA1/2 mutation testing is performed based on the Korean clinical practice guidelines for breast cancer." (PMID 38689097, 2024). "The contribution of genome wide methylation changes observed in peripheral blood of BRCA1 epimutation and germline mutation carriers, as well as women before diagnosis of breast cancer is poorly understood." (PMID 39529133, 2024). "Statements:Data on substitution of estrogens (ET), if necessary in combination with progestins (EPT), and breast cancer risk in BRCA1/2-pV carriers after RRSO is limited." (PMID 39259360, 2024). "For instance, mutations in the 5’ UTR of the BRCA1 gene have been found to affect translation efficiency and contribute to breast cancer aggressiveness." (PMID 38689247, 2024). "Data also suggest a relationship between BRCA1/2 mutations and poor prognostic factors, such as younger age at breast cancer diagnosis, high-grade tumors, and for BRCA1 mutation - a higher rate of triple-negative disease." (PMID 38365640, 2024). "The full model identified 5.8%, 12.9% and 24.0% of BRCA1/2 PV carriers with 5-year breast cancer risks of <1.65%, <3% and <5%, respectively, risk thresholds commonly used for different management and risk-reduction options." (PMID 38834293, 2024). "What is the breast cancer mortality risk of women with a BRCA1 or BRCA2 sequence variation after entering a magnetic resonance imaging (MRI) surveillance program?" (PMID 38421676, 2024). "Frameshift and missense mutations in breast cancer usually result in BRCA1 protein truncation, which is considered functionally deleterious." (PMID 38543119, 2024). "Cytoplasmic localization of ELAVL1 (embryonic lethal abnormal vision-like protein 1) and BRCA1 (breast cancer 1) gene mutations are associated with poor prognosis of breast cancer." (PMID 38378612, 2024). "Our results suggest the potential of iodine to reduce breast cancer risk in BRCA1 carriers after prophylactic oophorectomy but require further validation and investigation of its effect on ovarian cancer risk and overall mortality." (PMID 38892720, 2024). "In the realm of breast cancer research, the mutation frequency of the BRCA1 gene exhibits a broad spectrum, ranging from 1.8 to 36.9%, contingent upon the specific tumor subtype under consideration." (PMID 39217242, 2024).
breast cancer (continued). "Mutations in high-risk genes, such as breast cancer association 1 or 2 genes (BRCA1 or BRCA2), have long been linked with breast cancer heritability." (PMID 39596875, 2024). "Data from several studies indicate that RRSO is associated with a decrease in ovarian cancer (96%) and breast cancer (50%) occurrence and with a significant reduction in all-cause mortality rate, especially in BRCA1 mutation carriers." (PMID 38256099, 2024). "We found evidence of a statistically significant association with breast cancer risk for three genes, with ORs of 16.3 [95% CI: 4.0–66.7] (p = 0.0001) for BRCA1, 12.0 [95% CI: 2.9–45.9] for BRCA2 (p = 0.0001), and 7.3 [95% CI: 0.9–56.7] (p = 0.037) for ATM." (PMID 39684352, 2024). "The mutation rate of HRR pathway genes other than germline BRCA1/2 mutations is around 7% among all breast cancers and up to 17% in metastatic breast cancers." (PMID 38397152, 2024). "Germline BRCA1/2 mutations underlie tumorigenesis in approximately 5–15% of all ovarian cancer (OC), 3% of all breast cancer (BC) and in 10–20% of all triple negative BC cases." (PMID 38398132, 2024). "Young women who develop breast cancer before the age of 40 often harbor a pathogenic germline variant in the BRCA1 or BRCA2 gene." (PMID 38398129, 2024). "Germline ATM mutations predispose patients to familial breast cancer and are associated with HRD in BRCA1/2-wild type breast cancer patients." (PMID 39334297, 2024). "In this review, we explore the current status and obstacles associated with managing BRCA1/2-associated breast cancer in LMICs." (PMID 39421188, 2024). "In this study, we investigated the rate of CBC recurrence in Korean breast cancer patients according to the BRCA1/2 germline mutation status." (PMID 38254240, 2024). "The effect of HRT on breast cancer risk in BRCA1/2 mutation carriers is of particular importance, given the clear recommendation for HRT after RRBSO in premenopausal women." (PMID 38892081, 2024). "DNA damage response (DDR) pathways are important factors in the pathogenesis of breast cancer, with about 10% of breast cancers being caused by pathogenic germline mutations in homogenous recombination (HR)-related genes such as BRCA1/2." (PMID 39334297, 2024). "While BRCA1/BRCA2 mutation is associated with all breast cancers, TNBC exhibits a higher proportion with BRCA1/2 mutation (20% with a germline mutation) than other breast cancer subtypes." (PMID 39272915, 2024). "Because a subset of patients with breast cancer and a pathogenic variant in BRCA1/2 will choose BCT, continuing to study and report their long-term outcomes is important for ensuring that adequate evidence is available to inform patients." (PMID 38916888, 2024). "Germline ATM mutations confer an increased susceptibility to familial breast cancer and are associated with homologous recombination deficiency (HRD) in patients with BRCA1/2-wt breast cancer." (PMID 38539474, 2024). "How cost-effective are ovarian and breast cancer risk reduction strategies among women with pathogenic variants in individual cancer susceptibility genes (ie, BRCA1, BRCA2, PALB2, RAD51C, RAD51D, and BRIP1)?" (PMID 38334999, 2024). "In clinical practice, parity reduces breast cancer risk even among germline BRCA1/2 mutation carrier women." (PMID 39329990, 2024). "This cohort study examines the association between magnetic resonance imaging (MRI) surveillance and the risk of breast cancer mortality in women with BRCA1 or BRCA2 sequence variations." (PMID 38421676, 2024). "Up to 10 % of hereditary breast cancer cases are usually associated with germline variants in BRCA1 and BRCA2 and more aggressive disease course." (PMID 39011181, 2024). "Kuchenbaecker et al20 estimated contralateral breast cancer risk at 20 years to be 40% for BRCA1 variant carriers, but only 26% for BRCA2 variant carriers." (PMID 38916888, 2024).
breast cancer (continued). "Stigmatisation also deters women from seeking medical help promptly, particularly for BRCA1/2-associated breast cancers affecting younger, financially dependent women in LMICs, exacerbating delays in diagnosis and impeding treatment outcomes." (PMID 39421188, 2024). "Talazoparib, as a targeted PARP inhibitor, can effectively control the occurrence and development of breast cancer with BRCA1/2 gene mutation, and play a therapeutic role." (PMID 38886516, 2024). "Breast cancer is one of the tumors with the highest prevalence rate among women in the world, and its BRCA1/2 gene is a common mutation site." (PMID 38886516, 2024). "The patient undergoes regular breast screening because of the 72% cumulative risk of breast cancer development by the age of 80 years in BRCA1 variant carriers." (PMID 38524651, 2024). "In the mid-1990s, the identification of BRCA1/2 genes for breast cancer susceptibility led to testing breast MRI accuracy in screening women at increased risk." (PMID 38536530, 2024). "We focused on two high-frequency pathogenic mutations associated with hereditary breast cancer among Japanese patients—the BRCA1 Leu63Ter and the BRCA2 c.5576_5579delTTAA frameshift mutation." (PMID 38630824, 2024). "Researchers have targeted gene combinations such as BRCA1 and BRCA2, frequently found mutated in breast and ovarian cancer, and PARP1 and BRCA1, commonly mutated in breast cancer." (PMID 38195537, 2024). "Although adjuvant olaparib has been shown to improve survival in patients with BRCA1/2-mutated breast cancer, there is a paucity of evidence regarding its safety when combined with radiation therapy, which generates a significant amount of DNA damage." (PMID 38799106, 2024). "BRCA1 and 2 were the earliest discovered breast cancer susceptibility genes and are the genes with the highest penetrance." (PMID 38439896, 2024). "In the OlympiA trial (NCT02032823), adjuvant olaparib significantly enhanced invasive and distant disease-free survival in patients with high-risk, HER2-negative early breast cancer and germline BRCA1 or BRCA2 mutations, compared to a placebo." (PMID 39409871, 2024). "Germline pathogenic variants (PVs) in BRCA1/2 are the most common genetic risk factor for breast cancer, associated with poor prognostic factors." (PMID 38365640, 2024). "More than 40% BRCA1/2-mutant patients fail to respond to PARPi, especially Olaparib, causing minimal synthetic lethality in vitro in BRCA1-mutant human breast cancer HCC1937 and BRCA2-mutant human colorectal adenocarcinoma HCT-15 cells." (PMID 38543043, 2024). "Early work established that PARPi resistance can develop in a subset of breast cancer patients by reversion mutations in the BRCA1/2 genes that restore HR function and thereby abrogate cellular dependence on PARP1/2." (PMID 38956205, 2024). "Women harboring BRCA1 or BRCA2 (BRCA) germline pathogenic sequence variants (PSVs) are at a substantially increased lifetime risk for developing breast cancer (BC) estimated at 72% and 69%, respectively, at times diagnosed at an early age—< 40 years." (PMID 38379091, 2024). "In total, 364 patients had early onset breast cancer; the double mutation frequency was 1.65% (6/364), and the BRCA1/2 and PALB2 triple mutation frequency was 1.37% (5/364)." (PMID 38439896, 2024).
breast cancer (continued). "The interplay between DNA damage and autophagy is heavily influenced by DNA-damage repair (DDR) genes, such as breast cancer susceptibility genes 1 and 2 (BRCA1/BRCA2), and Fanconi anemia (FA) genes." (PMID 39199310, 2024). "Women with mutations in the BRCA1 gene have an increased risk of developing breast cancer and a tendency to establish Basal-like breast cancer." (PMID 39294728, 2024). "Before surgical planning, it is crucial to assess both the ipsilateral and unaffected contralateral breasts through imaging, as BRCA1/2 patients are at higher risk of multifocal or multicentric breast cancer." (PMID 39421188, 2024). "Poly(ADP-ribose) polymerase (PARP) plays an essential role in single-strand DNA repair, and PARP inhibitors have shown anticancer activity against HER2-negative breast cancer cells associated with BRCA1/BRCA2 mutations." (PMID 39690423, 2024). "BRCA1/2 mutations are indeed often associated with an increased number of tumor-infiltrating lymphocytes in different cancer types and tumor-associated inflammation in BRCA1-mutant breast cancer has significant positive prognostic value." (PMID 39544936, 2024). "Here, we examined the interaction between LYN kinase and BRCA1 loss-of-function in an in vivo mouse mammary tumour model, using conditional knockout Brca1 and Lyn alleles." (PMID 38149669, 2024). "This method amplifies the BRCA1 3232A > G and wild-type allele from DNA of human breast cancer cells, using recombinase polymerase amplification." (PMID 39189452, 2024). "Men carrying BRCA2 variants, and to a lesser extent BRCA1 variants, also exhibit heightened predispositions to breast cancer and prostate cancer." (PMID 38809921, 2024). "The pathogenic variants in the BRCA1 gene were strongly associated with bilaterality of breast cancer with an OR = 4.4 [95% CI: 1.9–10.1], p = 0.002)." (PMID 39684352, 2024). "The TBB phase 2 trial has expanded its monotherapy indication beyond BRCA1/2 mutation to breast cancer with other HR-related genetic mutations." (PMID 39334297, 2024). "It is part of an ongoing nationwide cohort established in 1997, which includes data from over 50 000 members of families with an increased risk of breast cancer and/or ovarian cancer, who were tested primarily for BRCA1 and BRCA2 genetic variants." (PMID 39384226, 2024). "Our study focused on assessing the effects of three newly identified BRCA1 exon 11 variants (c.1019T>C, c.2363T>G, and c.3192T>C) on breast cancer susceptibility." (PMID 38786046, 2024). "Overall, 1,710 patients had sporadic breast cancer; the BRCA1/2 double mutation frequency was 1.35% (23/1710), and the BRCA1/2 and PALB2 triple mutation frequency was 0.94% (16/1710)." (PMID 38439896, 2024). "Bilateral RRM confers a substantial reduction in breast cancer risk for unaffected individuals with PVs in BRCA1–2 genes, estimated at 90% and up to 95% when combined with RRSO." (PMID 38893140, 2024). "This is significant as KRT6B is typically expressed at higher levels in basal-like breast cancers, a type of cancer type common among BRCA1 mutation carriers." (PMID 38059556, 2024). "A recent study suggests that AURKA-HMMR, a genetic variant of AURKA, is linked to increased breast cancer risk in BRCA1 and BRCA2 mutation carriers." (PMID 38886738, 2024). "Mutations in BRCA1 account for the majority of hereditary breast cancer and predominantly result in truncation of the BRCA1 protein." (PMID 39596374, 2024). "Breast cancers associated with BRCA1 are predominantly triple-negative, characterized by a higher histological grade, elevated mitotic index, and significant lymphocytic infiltration." (PMID 39484212, 2024). "Specifically, the study showed that surveillance with breast MRI detected 56% of breast cancers in BRCA1 mutation carriers and 73% in BRCA2 mutation carriers." (PMID 38791944, 2024).
breast cancer (continued). "Next-generation sequencing studies have identified the presence of breast cancer susceptibility gene 1/2 (BRCA1/2) mutations in NSCLC patients, which are pathogenic variants associated with breast, ovarian, and prostate cancers." (PMID 38715777, 2024). "This case series demonstrates the use of rucaparib in metastatic breast cancer patients harboring both germline and somatic BRCA1/2 mutations, discussing the advancing landscape of targeted therapies in breast cancer management." (PMID 38910707, 2024). "In a recent Swedish publication, the percentage of carriers of a pathogenic variant in BRCA1 or BRCA2 among women diagnosed with breast cancer at 40 years or younger was 10.0% (105/1055 patients)." (PMID 38491334, 2024). "The model simulated costs and lifetime health outcomes of 42-year-old women with high-risk early-stage breast cancer and a known BRCA1/2 mutation who completed definitive primary therapy and neoadjuvant or adjuvant systemic therapy." (PMID 38170520, 2024). "In this study, the risks of ipsilateral and contralateral breast cancer events for patients with pathogenic BRCA1/2 variants who were treated with BCT were higher than reported for the general breast cancer population." (PMID 38916888, 2024). "This joint high prevalence is consistent with MYC and RAD21 being closely linked on amplicon 8q24 and frequently coamplified in BRCA1-mutated breast cancer." (PMID 38869771, 2024). "The risk of breast cancer in the general population is about 12%; however, when a BRCA1/2 mutation is present, the risk increases dramatically." (PMID 38791944, 2024). "Several studies have shown that BRCA1-mutated breast cancer cells are more sensitive to the cytotoxic effect of PARP inhibition than those that are BRCA1-intact." (PMID 39730675, 2024). "The role of BRCA1 in BP has been argued in the context of the high cardiovascular disease risk of BRCA1/2 mutation carriers and the comorbidity of hypertension and breast cancer." (PMID 38326862, 2024). "The goals of this qualitative study conducted among breast cancer survivors were to deepen our understanding of how FCR is experienced in the context of a BRCA1/2 mutation and to ascertain these women's needs in terms of psychological support." (PMID 38192174, 2024). "BRCA-1, a cfDNA marker associated with breast cancer and crucial for early breast cancer diagnosis, was selected as the target for detection." (PMID 38477342, 2024). "In order to monitor the elevated risk of breast cancer in women with pathogenic BRCA1 or BRCA2 gene mutations, MRI is used." (PMID 39449897, 2024). "In a study investigating the association between individuals’ PRSs and breast cancer risk, cancer susceptibility was determined on the basis of SNPs in women carrying pathogenic mutations in BRCA1 and BRCA213." (PMID 38491043, 2024). "Is adjuvant olaparib cost-effective in patients with early-stage breast cancer with high-risk disease and germline BRCA1/2 mutations?" (PMID 38170520, 2024). "The first case is of a young nulliparous woman with BRCA1-mutated ovarian cancer with a strong family history of ovarian cancer and breast cancer." (PMID 39272683, 2024). "It is possible that enhanced plasticity of BRCA1-mutant epithelial cells make these cells more susceptible to basal-like breast cancers, whereas limited plasticity makes tumors in BRCA2 mutation carriers similar to sporadic breast cancers." (PMID 38059556, 2024). "PALB2 PV/LPV, in addition to BRCA1/2, is also considered a high penetrance breast cancer susceptibility gene with an absolute lifetime risk of 44–63%." (PMID 39796639, 2024). "It involves inheriting a mutation in key breast cancer genes such as BRCA1, BRCA2 etc, which increases breast cancer risk, although more education frequently leads to better access to healthcare resources and tests." (PMID 39610935, 2024).